PVT1 (Pvt1 oncogene)
Diseases named in the same sentence as PVT1 in open-access papers (continued):
Sharing a sentence is not in itself a finding about the gene and the disease.
type 1 diabetes (5 papers, 2012 to 2024). "Plasmacytoma Variant translocation 1 (PVT1) is the first lncRNA suspects to be involved in kidney diseases, and two studies in 2007 reported the role of PVT1 in mediating susceptibility to ESRD caused by type 2 and type 1 diabetes, providing a rationale for PVT1 as a candidate gene for ESRD." (PMID 38390204, 2024). "We previously reported association of variants in the gene encoding plasmacytoma variant translocation 1 (PVT1) with ESRD attributed to type 2 diabetes (T2D), and subsequently validated this locus in a replication study comprised of individuals with ESRD attributed to type 1 diabetes (T1D)." (PMID 24204837, 2013).
abdominal aortic aneurysm (4 papers, 2021 to 2025). Enlargement and ballooning of the vessel that supplies arterial blood to the abdomen, pelvis and legs. "The long non-coding RNA plasmacytoma variant translocation 1 (lncRNA PVT1) has been implicated in the progression of abdominal aortic aneurysms (AAA)." (PMID 34898354, 2021). "Knockout of PVT1 can reverse angiotensin II‐induced changes in abdominal aortic aneurysm in mice, including the suppression of VSMC apoptosis and ECM destruction." (PMID 40289758, 2025). "PVT1 augments inflammation and pyroptosis of VSMCs in abdominal aortic aneurysm by repressing miR‐186‐5p expression." (PMID 40289758, 2025). "LncRNA PVT1 promoted MMP production and facilitated extracellular matrix degradation, leading to VSMC apoptosis and the formation of abdominal aortic aneurysm." (PMID 34775377, 2021). "In addition, a recent study noted that knockdown of PVT1 decreased levels of MMP-2 and MMP-9, augmented TIMP-1 expression, and suppressed serum levels of TNF-α, IL-1β, and IL-6 in VAMC and ApoE-/- mice of abdominal aortic aneurysm model." (PMID 34775377, 2021).
B cell lymphomas (4 papers, 2016 to 2022).
breast invasive carcinoma (4 papers, 2021 to 2023). "We first investigated the expression of PVT1 in TCGA database which included 1085 breast invasive carcinoma (BRCA) tissues and 170 normal tissues." (PMID 36941464, 2023). "This methodology has aroused a broad acknowledgment within the scientific community thanks to the encouraging results achieved when applied to breast invasive carcinoma, leading to the identification of PVT1, a long non-coding RNA functioning as ceRNA for the miR-200 family." (PMID 35524174, 2022). "The most significant prediction of the computational model implemented by SPINNAKER was the discovery of lncRNA PVT1 acting as ceRNA in breast invasive carcinoma (brca) dataset, where it antagonized the miR-200 family to regulate the expression of several messenger RNAs." (PMID 35524174, 2022). "Other studies have reported that miR-510, PVT1, CCAT1, and Linc00861 may play important roles in breast invasive carcinoma." (PMID 34220926, 2021).
Cerebral ischemia (4 papers, 2022 to 2026). Restriction of arterial blood supply to the brain associated with insufficient oxygenation to support the metabolic requirements of the tissue.
cholangiocarcinoma (4 papers, 2018 to 2024). A carcinoma that arises from the intrahepatic biliary tree (intrahepatic cholangiocarcinoma) or from the junction, or adjacent to the junction, of the right and left hepatic ducts (hilar cholangiocarcinoma). "Diagnostic value of lncRNAs for Cholangiocarcinoma: HULC(b), H19(c), LPAL2(d), C3P1(e), AC005550.3(f), APOC1P1(g), PVT1(h),and sensitivity: Sen." (PMID 30305026, 2018). "Similarly, PVT1 could bind epigenetic modification complexes (PRC2) for histone methylation in the promoter of ANGPTL4, and thus, promote the malignancy of Cholangiocarcinoma." (PMID 31335317, 2019).
chronic heart failure (4 papers, 2021 to 2025). "Knockdown of lncRNA PVT1 (identified as a candidate diagnostic biomarker) directly increased the expression of miR‐190a‐5p in vascular endothelial cell proliferation to inhibit chronic heart failure (CHF) progression." (PMID 35038974, 2022).
cutaneous melanoma (4 papers, 2017 to 2024). A primary melanoma arising from atypical melanocytes in the skin. "For example, plasmacytoma variant translocation 1 (PVT1), an lncRNA that resides near the Myc oncogene, is differentially expressed in cutaneous melanoma." (PMID 37629553, 2023). "The association between PVT1 expression and the clinicopathological parameters in patients with primary skin cutaneous melanoma in TCGA." (PMID 29244840, 2017). "DNA methylation was weakly and negatively correlated with PVT1 expression in skin melanoma (Pearson's r = -0.352, Spearman’s r = -0.480)." (PMID 29244840, 2017). "PVT1 is a driver lncRNA that was amplified in cervical squamous cell carcinoma and endocervical adenocarcinoma (CESC), LIHC and skin cutaneous melanoma (SKCM), which has been reported to be related to the progression of CESC, LIHC and SKCM." (PMID 28719033, 2017).
endometrial cancer (4 papers, 2022 to 2025). Primary or metastatic malignant neoplasm involving the endometrium (mucous membrane that lines the endometrial cavity). "Studies have found that a variety of lncRNAs are closely related to the factors involved in the occurrence and development of endometrial cancer, including plasmacytoma variant translocation 1 (PVT1)." (PMID 36869031, 2023). "Previous studies have suggested that plasmacytoma variant translocation 1 (PVT1) has a tumor-promoting effect on endometrial cancer; however, its mechanism of action in endometrial cancer stem cells (ECSCs) is unknown." (PMID 36869031, 2023). "Compared with normal endometrial tissue, PVT1 was significantly increased in endometrial cancer tissues." (PMID 36869031, 2023). "The expression of miR-136 in endometrial cancer tissues and ECSCs was found to be low, and it was negatively correlated with the expression of PVT1." (PMID 36869031, 2023). "In contrast, miR-136, which was lowly expressed in endometrial cancer and ECSCs, had the opposite effect, and knockdown miR-136 inhibited the anticancer effects of down-regulated PVT1." (PMID 36869031, 2023). "In endometrial cancer, PVT1 can bind to miRNAs, such as miR-612, miR-195-5p, and miR-508-5p, and regulates downstream target genes to promote cancer." (PMID 36869031, 2023). "Here, we found that PVT1 was highly expressed in endometrial cancers and ECSCs, correlated with poor patient prognosis, promoted the malignant behavior and the stemness of endometrial cancer cells (ECCs) and ECSCs." (PMID 36869031, 2023). "In conclusion, PVT1 plays a key role in endometrial cancer and is expected to become a new therapeutic target and be included in diagnostic screening methods in the future." (PMID 36195846, 2022). "The expression of PVT1 in endometrial cancer tissues and ECSCs were detected by qRT-PCR." (PMID 36869031, 2023). "We demonstrate that the PVT1/miR-136/Sox2/UPF1 axis plays an important role in the progression and maintenance of endometrial cancer." (PMID 36869031, 2023). "The PVT1/miR-136/Sox2/UPF1 axis provides a promising novel approach for the treatment of endometrial cancer, especially refractory endometrial cancer." (PMID 36869031, 2023). "We aimed to investigate the mechanism by which PVT1 regulates the expression of Sox2 and UPF1 by targeting miR-136, thereby affecting the malignant biological behavior and cell stemness of endometrial cancer cells (ECCs) and ECSCs." (PMID 36869031, 2023). "This indicates that Sox2 is a target gene of PVT1 to regulate miR-136 in endometrial cancer non-stem cells and ECSCs and has a tumor-promoting effect on endometrial cancer." (PMID 36869031, 2023). "We also detected the expression of PVT1 in endometrial cancer non-stem cells and stem cells and found that the expression of PVT1 in ECSCs was significantly higher than that in non-stem cells." (PMID 36869031, 2023). "After overexpressing PVT1 in endometrial cancer non-stem cells and ECSCs, the expression of miR-136 was significantly decreased as found in the qRT-PCR analysis." (PMID 36869031, 2023). "Our findings confirmed that the role of PVT1 in endometrial cancer non-stem cells and ECSCs is similar to that in other tumors and thereby provided a solid foundation for studying the function of PVT1 in endometrial cancer." (PMID 36869031, 2023). "After overexpressing PVT1 in endometrial cancer non-stem cells and ECSCs, the expression of Sox2 was significantly decreased as noted in the qRT-PCR analysis, while the expression of Sox2 increased after PVT1 knockdown." (PMID 36869031, 2023). "Both PVT1 and miR-136 were knocked down in endometrial cancer non-stem cells and stem cells." (PMID 36869031, 2023).
essential hypertension (4 papers, 2022 to 2025). Hypertension that presents without an identifiable cause. "This study reveals, for the first time, there is an association between rs80177647 and rs10956390 gene polymorphisms of PVT1 and the risk of essential hypertension in two populations in southern and northern China." (PMID 35036445, 2022). "Moreover, lncRNA PVT1 polymorphisms may be involved in the risk of essential hypertension in the Chinese population by regulating lipid levels." (PMID 37396592, 2023). "Therefore, we selected two tagSNPs of PVT1 (rs10956390 and rs80177647) to investigate whether they are contributing to the risk of hypertension in Chinese patients." (PMID 35036445, 2022). "By constructing the ceRNA regulatory network, we found that lncRNA PVT1-miR-139-5p-DCBLD2 has a potential ceRNA regulatory mechanism involved in the development of essential hypertension in Xinjiang Kazakh people." (PMID 37396592, 2023). "lncRNA PVT1-miR-139-5p-DCBLD2 was indicated to comprise a potential ceRNA regulatory mechanism involved in the development of essential hypertension in the Xinjiang Kazakh population." (PMID 37396592, 2023). "The potential role of lncRNA PVT1-miR-139-5p-DCBLD2 in the process of essential hypertension in Xinjiang Kazakh needs to be further verified in future studies." (PMID 37396592, 2023). "Furthermore, we constructed a ceRNA regulatory network related to differentially expressed lncRNAs, among which lncRNA PVT1-miR-139-5p-DCBLD2 may have a potential ceRNA regulatory mechanism in the occurrence of essential hypertension in Xinjiang Kazakh people." (PMID 37396592, 2023). "Our study reveals a new ceRNA regulatory network, lncRNA PVT1-miR-139-5p-DCBLD2, providing new insights into the mechanism of essential hypertension in Xinjiang Kazakh." (PMID 37396592, 2023). "Although the effects of PVT1 on hyperglycaemia and hypertension are not clear, our study has showed that proteinuria and kidney function decline were prevented by PVT1 inhibition." (PMID 36359234, 2022). "However, it is not clear whether PVT1 can regulate hypertension by affecting the blood lipid levels in the human plasma." (PMID 35036445, 2022). "Therefore, we hypothesized that lncRNA PVT1-miR-139-5p-DCBLD2 has a potential ceRNA regulatory mechanism in the occurrence of essential hypertension in Xinjiang Kazakh and that all RNAs in this ceRNA network may be biomarkers for the diagnosis of essential hypertension in this population." (PMID 37396592, 2023).
gastric adenocarcinoma (4 papers, 2020 to 2025). "A positive regulatory relationship existed between lncRNA DLEU1 and lncRNA PVT1, and the effects of lncRNA DLEU1 and lncRNA PVT1 on gastric adenocarcinoma were similar, both of which were highly expressed in tumor tissues." (PMID 34790582, 2021). "The results suggested that TMEM105, PVT1, FLJ22447, DLEU1, and LOC646588 closely related to the prognoses of patients with gastric adenocarcinoma." (PMID 34790582, 2021). "However, the hazard ratios of lncRNA PVT1 and lncRNA DLEU1 were less than 1, indicating that they were protective factors for gastric adenocarcinoma." (PMID 34790582, 2021). "In good agreement, increased PVT1 expression in COAD (colorectal adenocarcinoma), READ (rectal adenocarcinoma) and STAD (stomach adenocarcinoma) samples compared to the corresponding normal tissue was revealed using transcriptomic expression data available at the TCGA repository." (PMID 32083000, 2020).
Hodgkins lymphoma (4 papers, 2011 to 2014). A heterogeneous group of malignant lymphoid neoplasms of B-cell origin characterized histologically by the presence of Hodgkin and Reed-Sternberg (HRS) cells in the vast majority of cases. "Additionally, an association between genetic variants within PVT1 and Hodgkin’s lymphoma has also been postulated." (PMID 24944681, 2014). "Furthermore, genetic variants within PVT1 have been associated with Hodgkin's lymphoma." (PMID 21814516, 2011).
ischemic stroke (4 papers, 2021 to 2026). A stroke disorder caused by obstruction of blood flow to the brain, due to thrombotic (local blood clot formation) or embolic (due to a blood clot or other material traveling from another site) event. "Multiple studies reported differential expression of lncRNAs H19, GAS5, PVT1, TUG1, and MALAT1 in ischemic stroke." (PMID 39766887, 2024).
papillary thyroid carcinoma (4 papers, 2020 to 2025). "LncRNA PVT1 enhances the viability and invasion of papillary thyroid carcinoma cells by functioning as ceRNA of microRNA-30a to mediate the expression of insulin like growth factor 1 receptor." (PMID 32228518, 2020).
preeclampsia (4 papers, 2018 to 2023). Preeclampsia is a hypertensive disorder of pregnancy that is characterized by new-onset hypertension with proteinuria presenting after 20 weeks of gestation, and depending on mild or severe forms may initially present with severe headache, visual disturbances, and hyperreflexia. "Here, we identified a lncRNA,PVT1, whose expression was down‐regulated in qRT‐PCR analyses in severe preeclampsia." (PMID 29193797, 2018). "Reduced expression of lncRNA plasmacytoma variant translocation 1 (PVT1) was observed in the placentas of patients with GDM and preeclampsia, and knocking down PVT1 enhanced apoptosis and inhibited the proliferation, migration, and invasion of trophoblast cells through the PI3K/Akt pathway." (PMID 35505296, 2022). "Our results provide important insights into the role of PVT1 in the aberrant characteristics of trophoblasts in PE and may act as a potential biomarker for preeclampsia diagnosis and therapy." (PMID 29193797, 2018). "To ascertain whether PVT1 was differentially expressed in placental samples from severe preeclampsia women, we quantified PVT1 expression by qRT‐PCR in 52 paired clinic placental samples from women with normal pregnancies and severe PE." (PMID 29193797, 2018). "Altogether, our study suggests that PVT1 could play an essential role in preeclampsia progression and probably acts as a latent therapeutic marker; thus, it might be a useful prognostic marker when evaluating new therapies for patients with preeclampsia." (PMID 29193797, 2018).
sarcoma (4 papers, 2019 to 2020). A usually aggressive malignant neoplasm of the soft tissue or bone. "Time-dependent ROC showed that PVT1 expression can predict the OS at 1 and 2 years for sarcoma patients, with an area under the curve (AUC) of 0.604 and 0.613, respectively." (PMID 31598169, 2019). "Although the prognosis analysis of TCGA sarcoma PVT1 was analyzed, both of these previous studies extracted the PVT1 expression data from a third-party data integration website of TCGA." (PMID 31598169, 2019). "Consistent with previous studies, we found that PVT1 is a biomarker of a poor prognosis in sarcoma and can be a novel therapeutic target." (PMID 31598169, 2019). "Weighted gene co-expression network analysis identified ten hub differentially expressed genes (DEGs) between sarcoma tissues with low and overexpression of PVT1, and substantiated that these DEGs have a complex co-expression network relationship." (PMID 31598169, 2019). "Its underlying mechanism is revealed by GSEA, and CMap offers three candidate drugs for the individualized targeted therapy of sarcoma patients with overexpression of PVT1." (PMID 31598169, 2019). "The present study aims to identify the potential clinical application and molecular mechanism of PVT1 in patients with sarcomas by mining an RNA sequencing (RNA-seq) dataset from TCGA and by using multiple genome-wide analysis approaches." (PMID 31598169, 2019). "Our findings indicate that PVT1 can serve as a prognosis biomarker in patients with sarcoma, and performed well in short-term OS prediction." (PMID 31598169, 2019). "Furthermore, we also used the genome-wide RNA-seq dataset to perform a GSEA between different PVT1 expression groups and identified the potential mechanism of PVT1 in sarcoma prognosis." (PMID 31598169, 2019). "CMap analysis has identified that antipyrine, ondansetron, and econazole may be candidate targeted drugs for sarcoma patients with PVT1 overexpression." (PMID 31598169, 2019). "Through literature review indicated that the three small-molecule drugs for PVT1 targeted therapy identified in the present study have not been reported to be associated with sarcoma treatment in previous studies." (PMID 31598169, 2019). "Furthermore, we also identified three potential small-molecule drugs (antipyrine, ondansetron, and econazole) for targeted therapy of PVT1 overexpression in sarcoma patients." (PMID 31598169, 2019). "Most of these GSEA enrichment results of PVT1 in sarcoma were consistent with previous studies, and we infer that PVT1 can be a novel therapeutic target for sarcoma and may have clinical application values in sarcoma prognosis monitoring and the designation of treatment strategy." (PMID 31598169, 2019). "The potential molecular mechanism of PVT1 in sarcoma may involve the posttranscriptional regulation of gene expression, tumor invasiveness and metastasis, osteoblast differentiation and development, apoptosis, NF-KB, Wnt, and apoptotic related signaling pathways." (PMID 31598169, 2019). "Second, because the sample size in the present study was small, we did not observe that PVT1 showed a good prognostic predictive ability in all subgroups of sarcoma." (PMID 31598169, 2019). "However, a comprehensive investigation of the clinical values of PVT1 in sarcoma has not been reported." (PMID 31598169, 2019).
small cell lung carcinoma (4 papers, 2018 to 2024). Small cell lung cancer (SCLC) is a highly aggressive malignant neoplasm, accounting for 10-15% of lung cancer cases, characterized byrapid growth, and early metastasis. "It was reported that depletion of PVT1 expression resulted in the reduction of migration and invasion capacities of small cell lung cancer (SCLC) cells in vitro." (PMID 33817293, 2021). "In the context of LC, numerous studies have demonstrated a consistent upregulation of PVT1 across different subtypes of the disease, including NSCLC and small-cell lung cancer (SCLC)." (PMID 39452836, 2024).